TJAP1 (tight junction associated protein 1)
Description:
Plays a role in regulating the structure of the Golgi apparatus.
Synonyms: PILT; TJP4
Tractability: Antibody: UniProt places it where antibodies can reach, with high confidence; its Gene Ontology location is reachable by antibodies, with medium confidence. PROTAC: ubiquitination databases record sites on it; its protein half-life has been measured.
Gene: Protein-coding gene on chromosome 6 (43,477,523 to 43,506,562, forward strand). Ensembl gene ENSG00000137221.
Subcellular location: Golgi apparatus, trans-Golgi network; Cell junction, tight junction; Cell membrane
Subcellular location (Human Protein Atlas): Golgi apparatus
Gene Ontology:
Molecular function: protein binding
Biological process: Golgi organization
Cellular component: Golgi apparatus; plasma membrane; trans-Golgi network; bicellular tight junction; cytoplasm; endosome
Genetic constraint (gnomAD): Loss-of-function variants: 29 observed, 41.46 expected, observed/expected ratio (o/e) 0.7, 90% interval 0.52 to 0.95. The upper end of that interval is the gene's LOEUF score, 0.95, which puts it in group 4 of 6, group 1 being the genes least tolerant of losing a copy. Missense variants: 689 observed, 708.47 expected, observed/expected ratio (o/e) 0.97, 90% interval 0.91 to 1.04. Synonymous variants: 251 observed, 279.42 expected, observed/expected ratio (o/e) 0.9, 90% interval 0.81 to 1.
Homologues: Orthologues: chimpanzee TJAP1 (99% identical), macaque TJAP1 (96% identical), pig TJAP1 (92% identical), rabbit TJAP1 (92% identical), dog TJAP1 (90% identical), guinea pig TJAP1 (88% identical), mouse Tjap1 (86% identical).
Diseases named in the same sentence as TJAP1 in open-access papers:
TJAP1 is named in the same sentence as 13 diseases in open-access papers, as found by Europe PMC text mining. Sharing a sentence is not in itself a finding about the gene and the disease. The quoted sentences say what the papers report.
ischemic stroke (1 paper, 2024). A stroke disorder caused by obstruction of blood flow to the brain, due to thrombotic (local blood clot formation) or embolic (due to a blood clot or other material traveling from another site) event. "In the adult brain, TJAP-1 and JAM3 (alias JAM-C) are important for blood–brain barrier integrity and were identified as potential therapeutic targets of the protective microRNA-132/212 after ischemic stroke." (PMID 38338705, 2024).
Stroke (1 paper, 2021). Sudden impairment of blood flow to a part of the brain due to occlusion or rupture of an artery to the brain. "In the acute phase after stroke, CRTC1 KO mice exhibited a statistically significant increase in TJAP-1 expression and Claudin-1 expression in comparison with WT mice." (PMID 34880207, 2021). "In this study, TJAP-1 and Claudin-1 exhibited a significant increase in CRTC1 KO mice compared with WT mice, leading to BBB damage by Claudin-5/Claudin-1 dysregulation in the CRTC1 KO brain after stroke." (PMID 34880207, 2021).
infection (12 papers, 2009 to 2025). The state of being infected such as from the introduction of a foreign agent such as serum, vaccine, antigenic substance or organism. "In response to pathogen infection, the receptors such as EGFR, ERBB2, CDH1, HSP90B1, and TJAP1 at the host membrane interact with pathogen cell wall proteins to start inducing endocytosis." (PMID 30769958, 2019). "In the infection progression of C. albicans SC5314, orf19.1816 (ALS3) plays a significant role in cell adhesion and endocytosis induction by interacting with EGFR, ERBB2 (HER2), CDH1 (E-cadherin), HSP90B1 and TJAP1 (TJP4)." (PMID 30769958, 2019).
tumor (1 paper, 2024). "metascape analysis of the three tumor proteins of interest indicated that FABP7, TJAP1 and AHSP were associated with fatty‐acid transport (GO:0015908), Golgi organization (GO:0007030) and hemoglobin metabolic process (GO:0020027), respectively." (PMID 38803161, 2024). "For tumor samples, only three of the 5422 normalized proteins displayed significant downregulation in the STS group: FABP7, TJAP1 and AHSP." (PMID 38803161, 2024). "The TCGA‐GB transcriptomic dataset was used to validate the prognostic value of the three tumor proteins of interest (AHSP, FABP7 and TJAP1) at the mRNA level." (PMID 38803161, 2024). "The three tumor proteins of interest (AHSP, FABP7 and TJAP1) were downregulated in the STS group and were not identified in the proteome of serum samples from GB patients." (PMID 38803161, 2024).
TJAP1 also shares sentences with these, for which no sentence is quoted: bacteremia (2 papers); Sepsis (2); acute pneumonia (1); asthma (1); Constipation (1); corneal infection (1); Hydrocephalus (1); myonecrosis (1); tularemia (1).